HIF1A (hypoxia inducible factor 1 subunit alpha)
Diseases named in the same sentence as HIF1A in open-access papers (continued):
Sharing a sentence is not in itself a finding about the gene and the disease.
tumor (continued). "Furthermore, expression of HIF-1α is regulated by PI3K which, as previously discussed, has been linked to cancer development and progression as well as tumour radioresistance." (PMID 36233505, 2022). "Tumor cells undergo metabolic reprogramming through several regulatory pathways such as HIF-1α, PI3K/Akt or c-myc, resulting in an overexpression of the glucose transporters (GLUT1, GLUT2 and GLUT4) found expressed in PDAC, as well as in the upregulation of several glycolytic genes." (PMID 36142542, 2022). "To demonstrate the relationship between HIF-1α activity and PD-L1 protein expression in tumor cells in vivo, we transduced 4T1 cells with a lentiviral transcription factor reporter construct containing the core hypoxia-response element (HRE) motif upstream of an EGFP reporter." (PMID 35239514, 2022). "The catalytic decomposition of endogenous H2O2 could be utilized to produce oxygen for the downregulation of HIF-1α protein to reverse the tumor hypoxic microenvironment." (PMID 35565979, 2022). "Meanwhile, the remission of tumor hypoxia was further verified by down-regulation of HIF-1α expression level, indicating that released oxygen could relieve intratumoral hypoxia and enhance production of ROS." (PMID 35413984, 2022). "The metformin-induced tumor growth delay and enhancement of the radiation-induced tumor growth delay may be attributable, at least in part, to the suppression of the HIF-1α/PD-L1 pathway and increase in T-cell-mediated anti-tumor immunity." (PMID 35805044, 2022). "Similarly, the human NK cell line NKL expressed HIF-1α upon IL-2 stimulation in hypoxia and exhibited improved anti-tumor cytotoxicity and IFN-γ secretion." (PMID 34999917, 2022). "The results suggest that HIF-1α also regulates PD-L1 expression on tumor cells in vivo." (PMID 35239514, 2022). "Moreover, in contrast to non-tumor tissues, higher expression of HIF-1α was also observed in CRC tissues." (PMID 34969360, 2022). "Some studies showed that HIF-2a stimulates tumorigenesis while HIF-1a acts as a tumor suppressor." (PMID 36294785, 2022). "Moreover, one study showed that HIF-1α protein expression increased with BBG treatment in tumor cells." (PMID 36385758, 2022). "HIF-1α inhibition in vivo downregulated PD-1 expression, upregulated cytolytic effector molecules granzyme B and perforin, and decreased apoptosis in TILs in the tumor microenvironment." (PMID 35499071, 2022). "As an example, in prostate cancer, the transfer of pyruvate kinase 2 from the primary tumor to bone marrow stromal cells results in the increased expression of CXCL12 in the bone marrow in an HIF1α-dependent manner, favoring the establishment of metastatic cells in bone." (PMID 36497411, 2022). "Furthermore, PI3K regulates expression of hypoxia-inducible factor-1α (HIF-1α), which then promotes growth and progression of hypoxic tumours primarily through increasing vascularisation and glucose metabolism." (PMID 36233505, 2022). "In areas of tumor hypoxia, hypoxia can inhibit intratumor cytotoxic T cell responses by upregulating the expression of PD-L1 on the surface of TAMs via hypoxia-inducible factor 1-α (HIF-1α)." (PMID 35965509, 2022). "In addition, high doses of RT (HDRT) also exhibited pro-tumor effects by inducing HIF-1α/TGF-β signaling, increasing the number of CAFs and promoting fibrosis and remodeling of TIME." (PMID 36532071, 2022). "HIF-1a enhances the expression of miR-210 in tumor-localized MDSC." (PMID 36226050, 2022). "In addition to tumor cells, HIF-1α also operates in the immune suppressive cells present in hypoxic tumor microenvironment." (PMID 35795658, 2022). "Hypoxia and HIF-1α also play an important role in tumor angiogenesis." (PMID 36439496, 2022). "In the most recent study, the expression of HIF-1α was identified in 104 tumor biopsies." (PMID 36358811, 2022).
tumor (continued). "For instance, the hypoxic microenvironment can result in overexpression of HIF-1α, which is capable of modulating gene expression relevant to tumor proliferation, invasion and metastasis to facilitate the resistance to O2-dependent antitumor strategies, such as chemotherapy, PDT and RT." (PMID 36096856, 2022). "mRNA expression of Mmp9, Egfr and Hmox1 (tumor progression), Timp1 and Timp2 (inhibitors of metalloproteinases) and Hif1α (hypoxia) evaluated in lung homogenates was significantly augmented in LLC-challenged Igf1rfl/fl mice, remaining unaltered in CreERT2 mice." (PMID 35688943, 2022). "COMMD1 can disrupt HIF-1α/β dimerization and inhibit human tumor cell invasion." (PMID 35399735, 2022). "The HIF-1α biomarker is increased in tumor cells and could be used as a prognostic marker because it affects the p21 protein." (PMID 35956111, 2022). "HIF1α plays a crucial role in providing a favorable environment for tumor growth and metastasis." (PMID 35941273, 2022). "In this review, we focus on HIF-1α as the most well-studied isoform in tumor biology." (PMID 36551540, 2022). "Altogether, the results demonstrated that a HIF1A-RRAGB-mTORC1 positive feedback loop drives tumor progression in CRC, which could be interrupted by circEXOC6B." (PMID 35739524, 2022). "In addition, HIF-1α induces VEGF by recruitment of bone marrow-derived CD45+ cells which secretes metalloproteinase-9 (MMP-9) in the tumor site." (PMID 36014432, 2022). "Given the large areas of central necrosis seen in tumor sections from treated mice, we speculated that fenofibrate might potentiate hypoxic cell death through modulation of HIF1α." (PMID 35053444, 2022). "The release of BEZ235 from H-APBC in acid microenvironment could mitigate PI3K/mTOR signal and resist HIF-1α-dependent tumor hypoxia adaptation." (PMID 35413842, 2022). "Since GBM contains several tumor microenvironments (TMEs) with irregular distributions of signaling networks, we wondered whether the gene expression levels of KDM5C, BDNF, and HIF1A differed in distinct GBM tumor areas." (PMID 36142158, 2022). "Hypoxia-inducible factor-1α (HIF-1α) is a potential target for suppressing tumor metastasis." (PMID 36296726, 2022). "The reasons for their lack of efficacy in vivo may be related to the heterogeneity of tumor cells, the complexity of hypoxic microenvironment, and the fact that only HIF-1α targets have been studied while few HIF-2α inhibitors." (PMID 36226050, 2022). "Moreover, HIF-1α also increases PD-L1 expression on tumor cells and suppresses immune cell responses by targeting PD-1 on activated T cells." (PMID 36532071, 2022). "CoCl2-induced HIF-1α expression could reverse the inhibitory effect of docetaxel in tumor glycolysis, including glycolytic genes expression, lactate production and glucose uptake." (PMID 36536346, 2022). "A broad understanding of tumor cells’ adaptive signaling pathway using HIF-1α/β might be critical for improving therapeutic strategies against malignant tumors." (PMID 36183290, 2022). "Given that miR-138-5p affects both tumour cells and endothelial cells and regulates the expression level of HIF-1α in endothelial cells, we hypothesized that miR-138-5p might suppress tumour growth by blocking blood nutrient supply." (PMID 35669101, 2022). "Thus, in tumor cells in hypoxic areas, HIF1α and the expression of the lactate transporter MCT4 (monocarboxylate transporter-4) are induced." (PMID 35053485, 2022). "Additionally, our mouse data extended the knowledge concerning the fate of HIF-1α in the tumor microenvironment." (PMID 36183290, 2022). "Moreover, HIF-1α expression and AKT phosphorylation were correlated with VM formation in tumor samples from EBV-associated GC patients." (PMID 35681691, 2022). "Interestingly, IR tends to diminish HOTAIR and HIF1α levels in cells, which results in decreasing cell viability and tumor growth, as well as inhibiting apoptosis." (PMID 36294743, 2022).
tumor (continued). "Thus, the positive feedback effect of lactate involved in HIF-1α upregulation will further accelerate tumor cell release of sEVs and thus increase tumor aggressiveness." (PMID 36531060, 2022). "iNOS, COX-2 and HIF-1α may act synergistically, and inhibition of iNOS may reduce both COX-2 and HIF-1α expression in tumours, enhancing the efficacy of cancer therapy." (PMID 35660630, 2022). "Also, on vascular endothelial cells, cabozantinib would prevent HIF1A modulation, inhibiting tumour invasion." (PMID 35106125, 2022). "Generally, certain molecular pathways, including phosphoinoisitide dependent kinase l, mTOR-RICTOR kinases and PI3K-AKT, could be affected or controlled by HIF-1α, which is itself an attractive drug target for clinical tumor treatment." (PMID 35607406, 2022). "Our studies indicate that HITT is a multifunctional lncRNA that produces tumor-suppressive effects by either inhibiting hypoxia inducible factor-1α (HIF-1α) synthesis-induced angiogenesis or attenuating DNA damage, including ataxia telangiectasia-mutated gene (ATM) activation." (PMID 35909936, 2022). "The hybrid nanoparticles utilize the catalytic decomposition of endogenous H2O2 to produce oxygen for the downregulation of the hypoxia-inducible factor 1 subunit alpha (HIF-1α) protein, which could reverse the tumor hypoxic microenvironment." (PMID 35565979, 2022). "Furthermore, the expressions of HIF-1α and its downstream metastasis-associated proteins including MMP-2 and VEGF in tumor sites were notably inhibited." (PMID 35893790, 2022). "Therefore, our findings further enrich the role of HIF1α in the process of energy metabolism of tumor cells." (PMID 35153295, 2022). "The tumor cells at the core are challenged with oxygen deprivation and hence must adapt to the environmental challenge of hypoxia by activating the hypoxia-inducible factor-1 α (HIF-1α) transcription factor." (PMID 35912218, 2022). "At minimum, HIF1α is expendable once a tumor is established." (PMID 36040300, 2022). "Thus, as another HIF1A target that contributes to tumor immune escape, HIF1A upregulates VSIR expression under hypoxia." (PMID 35659268, 2022). "The up-regulation of NOX4 promotes tumor angiogenesis by stabilizing HIF-1α in mice." (PMID 36297636, 2022). "We postulated that CRMP2 might regulate tumor progression via HIF-1α-glycolysis signaling pathway which has been found in several human malignances." (PMID 35927239, 2022). "Moreover, in hypoxic conditions, intratumor cytokines, growth factors, and other signaling molecules stimulate HIF-1α expression and activity in tumor cells by different molecular mechanisms such as PI3K or MAPK." (PMID 35845307, 2022). "For example, activated HIF-1α in tumors downregulates Dicer expression by inducing ubiquitination of the E3 ligase Parkin, and further reduces the expression of tumor suppressor miRNAs, including let-7 and miR-200b, which promotes EMT and metastasis in tumor-bearing mice." (PMID 36139427, 2022). "HIF-1α downregulation by Sestrin2 decreased VEGF which is crucial for intra-tumor angiogenesis." (PMID 35527284, 2022). "Approximately 45.9% of the tumour showed HIF-1α expression (141/307)." (PMID 35659359, 2022). "Especially, the pro-tumor effect of HIF-1α on malignant progression has been extensively reported." (PMID 36209275, 2022). "Overall, tumor-infiltrating HIF-1α cKO NK cells displayed higher anti-tumor activity." (PMID 35769460, 2022). "Given that HIF-1α is a tumor angiogenic factor, the present study suggests that CX-4945 may have a potential anti-angiogenic effect in HuCCT-1 cells." (PMID 35683032, 2022). "Indeed, immunofluorescence analysis of the tumor slices indicated suppression of HIF-1α and CD31 proteins, which is a clear indication of hypoxia reversion." (PMID 36139623, 2022). "HIF1α is believed to exert antiangiogenic effects and is related to tumor vessel abnormalities." (PMID 34738103, 2022).
tumor (continued). "Uncovering the precise mechanisms by which HIF-1α induces tumor progression and chemoresistance in GC may offer new strategies to target the HIF-1α pathway and improve treatment outcomes in GC." (PMID 35681691, 2022). "Moreover, intermittent hypoxia in a solid tumor environment induced the upregulation of tumor-evasive factors, such as IL-10, HIF-1α, TGF-β1, and TNF-α." (PMID 36233088, 2022). "Importantly, our previous studies showed that the level of HIF-1α and the activities of NF-κB and STAT-3 were induced and associated with tumor development in RT-R-MDA-MB-231 cells compared to MDA-MB-231 cells." (PMID 36077661, 2022). "Finally, the xenograft tumour assay using nude mice showed that COMMD3 knockdown inhibited tumor growth and the expression of HIF1α, VEGF and CD34." (PMID 35399735, 2022). "Thus, HIF-1α plays a role in regulating NK cell glucose metabolism, anti-tumor, and anti-infection during hypoxia." (PMID 36761171, 2022). "HIF-1α is a prognostic marker related to the overall poor prognosis of tumor patients." (PMID 35800058, 2022). "Tumor glycolysis, characterized by an adaptive switch from oxidative respiration to glycolysis, even in the presence of oxygen, confers a survival advantage to cancerous cells, which has demonstrated to be regulated by HIF-1α." (PMID 36536346, 2022). "Moreover, increased lactate generation enhances the tumor-promoting capacity of MDSCs through the G protein-coupled receptor 81 (GPR81)/mTOR/HIF-1α/STAT3 pathway in PDAC." (PMID 36200045, 2022). "Clinically, targeting lncRNA HIFAL and HIF-1α significantly reduced their impact on tumor growth." (PMID 36226050, 2022). "Moreover, MI inhibited xenograft tumor growth in vivo and decreased the expression of Nox4, NF-κB, and HIF-1α." (PMID 35293283, 2022). "Furthermore, hypoxia-inducible factor-1α (HIF-1α) staining was conducted to verify that the Oxygen tank reversed tumor cell hypoxia." (PMID 36138489, 2022). "Angiogenesis induced by the HIF-1α/VEGF pathway is pivotal for tumor migration and invasion in CRC." (PMID 35928881, 2022). "In the hypoxic TME, HIF‐1α‐mediated FAO inhibition facilitates tumor progression." (PMID 34964283, 2022). "Notably, the production and accumulation of an important factor, HIF-1α, induced by tumor cells in hypoxia plays an important role in a range of regulatory responses in tumors." (PMID 36139386, 2022). "More importantly, while the hypoxia inhibits the function of PHD, HIF-1α will be activated and promotes the expression of downstream target genes, which further promotes the formation of hypoxic microenvironment and the progress of tumor cells." (PMID 36212414, 2022). "Moreover, emerging evidence indicates that ANGPTL4 expression, induced by hypoxia-inducible factor 1 alpha (HIF1α) under hypoxic conditions, promotes tumor cells aggressiveness and metastasis." (PMID 35392474, 2022). "HIF1α-mediated effects on tumour mass have been demonstrated previously." (PMID 34708297, 2022). "Inhibition of HIF-1α with small molecules such as metformin downregulates immunosuppressive pathways, including the expression of immune checkpoints, and it improves or restores the anti-tumor immunity stimulated by irradiation." (PMID 35805044, 2022). "As hypoxia increasingly dominates the tumor, degradation of hypoxia-inducible factor 1-alpha (HIF-1α) is decreased, resulting in the expression of angiogenesis-promoting genes, such as vascular endothelial growth factor (VEGF) and basic fibroblast growth factor (bFGF)." (PMID 36436127, 2022). "In addition, the expression of HIF-1α expression, using electrophoresis combined with Western blotting, was assessed on tumor biopsy samples and organs, including lungs and kidneys." (PMID 35456681, 2022). "Interestingly, we found a co-overexpression of KDM5C and the tumor prognostic genes HIF1A, p75 and survivin (alias BIRC5), involved in hypoxia-mediated mechanisms, as aggressiveness and a poor therapeutic response." (PMID 36142158, 2022).
tumor (continued). "Furthermore, the hypoxia of the visceral adipocyte but not the peripheral adipocyte would boost the production of the hypoxia factor 1α (HIF1α) and inflammation, a state that would stimulate tumor progression." (PMID 36139681, 2022). "Studies suggested that HIF-1α may develop resistance to conventional therapies through a series of signaling pathways including drug effusion, tumor stem cell enrichment, autophagy and apoptosis." (PMID 36003773, 2022). "HIF1A is a critical transcriptional regulator that mediates the adaptive response of cells to the hypoxic microenvironment, promotes tumor angiogenesis, regulates metabolic reprogramming, accelerates the epithelial-mesenchymal transition (EMT), and increases radio-/chemotherapy resistance." (PMID 35659268, 2022). "LEM inhibits PD-L1 in tumor cells by targeting the HIF-1α/PD-L1 axis." (PMID 35239514, 2022). "However, while hypoxia is generally associated with poor prognosis, the prognostic role of HIF1A and EPAS1 differs between tumor types." (PMID 36230822, 2022). "SRC-1 promotes tumor angiogenesis by raising HIF1α-mediated VEGFA expression." (PMID 34696659, 2022). "The study showed that the H-APBC could produce ROS upon light irradiation and release of BEZ235 from H-APBC in acid microenvironment could mitigate PI3K/mTOR signal and resist HIF-1α-dependent tumor hypoxia adaptation." (PMID 36532768, 2022). "SMAD7, HIF-1α gene, and HIF-1α protein may be jointly implicated in cancer development and prognosis, while SEC13, GHRL, and lncRNA GHRLOS may act as tumor suppressors." (PMID 35449150, 2022). "Moreover, HIF-1α overexpression induces β-catenin nuclear location, leading to high rates of proliferation, tumor growth, and radioresistance." (PMID 35741024, 2022). "HIF-1α regulates tumor angiogenesis by regulating various angiogenic factors under hypoxia." (PMID 35795276, 2022). "The IHS scores of HIF-1α in tumor tissue of mice between the group C+W and W, between the group W and C, and between the group C and M were different without statistical significance (H = 2.200, P = 1.000; H = 7.200, P = 0.201; and H = 1.800, P = 1.000, respectively)." (PMID 35693265, 2022). "Thus, hypoxia-induced EMT and HIF-1α expression can regulate the expression of angiogenesis and promote tumor cell metastasis." (PMID 35155248, 2022). "The degradation of HIF-1α inhibits the metabolic reprogramming of tumors and tumor growth." (PMID 35392171, 2022). "Tumor-derived exosomes contain pro-EMT molecules, such as TGFβ, HIF1α, and β-catenin, that do not only aid tumor cell immune evasion but enhance the invasive and migratory abilities of recipient cells, hence, contributing to stromal remodeling and premetastatic niche formation." (PMID 36233088, 2022). "However, in this study, we have demonstrated that docetaxel repressed tumor progression through Smad3-mediated tumor glycolysis in vivo and in vitro through HIF-1α, thereby inhibiting cell proliferation." (PMID 36536346, 2022). "Although these studies support a tumor-promoting role for HIF-2α in ccRCC, recent data suggest that HIF-1α may also contribute to ccRCC progression in the context of the complex tumor microenvironment." (PMID 36097192, 2022). "Stabilization/upregulation of HIF-1α is important in tumor cells because it drives a transcriptional program that inhibits apoptosis, enhances cell migration and promotes angiogenesis, while also impacting the host anti-tumor immune response." (PMID 35018216, 2022). "HIF-1α plays a key role in generating an inflammatory response within the tumor microenvironment." (PMID 36014432, 2022). "We hypothesize that solid tumor formation in vivo may lead to various microenvironmental conditions, including hypoxia, that may reactivate essential stemness genes such as MYC and HIF1A to reprogram tumor cells into stem-like cells." (PMID 35404029, 2022).